FBXO17 (F-box protein 17)
Description:
Substrate-recognition component of the SCF (SKP1-CUL1-F-box protein)-type E3 ubiquitin ligase complex. Able to recognize and bind denatured glycoproteins, which are modified with complex-type oligosaccharides. Also recognizes sulfated glycans. Does not bind high-mannose glycoproteins.
Synonyms: FBG4; FBX17; FBX26; FBXO26; FLJ25205; MGC9379; FLJ11798
Tractability: No criterion of Open Targets' tractability assessment is met for any kind of drug.
Gene: Protein-coding gene on chromosome 19 (38,941,401 to 38,976,773, reverse strand). Ensembl gene ENSG00000269190.
Pathways (Reactome):
Immune System: Antigen processing: Ubiquitination & Proteasome degradation
Metabolism of proteins: Neddylation
Gene Ontology:
Molecular function: protein binding; ubiquitin protein ligase activity
Biological process: ERAD pathway; glycoprotein catabolic process; SCF-dependent proteasomal ubiquitin-dependent protein catabolic process
Cellular component: SCF ubiquitin ligase complex; cytoplasm; cytosol
Genetic constraint (gnomAD): Loss-of-function variants: 45 observed, 32.83 expected, observed/expected ratio (o/e) 1.37, 90% interval 1.08 to 1.75. The upper end of that interval is the gene's LOEUF score, 1.75, which puts it in group 6 of 6, group 1 being the genes least tolerant of losing a copy. Missense variants: 397 observed, 310.7 expected, observed/expected ratio (o/e) 1.28, 90% interval 1.18 to 1.39. Synonymous variants: 159 observed, 129.47 expected, observed/expected ratio (o/e) 1.23, 90% interval 1.08 to 1.4.
Homologues: Orthologues: chimpanzee FBXO17 (100% identical), macaque FBXO17 (99% identical), guinea pig FBXO17 (87% identical), mouse Fbxo17 (86% identical), pig FBXO17 (86% identical), rat Fbxo17 (83% identical), dog FBXO17 (79% identical), rabbit FBXO17 (76% identical). Paralogues in human: FBXO27 (59% identical), FBXO2 (35% identical), FBXO6 (32% identical), FBXO44 (31% identical), NCCRP1 (26% identical).
Diseases named in the same sentence as FBXO17 in open-access papers:
FBXO17 is named in the same sentence as 20 diseases in open-access papers, as found by Europe PMC text mining. Sharing a sentence is not in itself a finding about the gene and the disease. The quoted sentences say what the papers report.
glioma (9 papers, 2018 to 2025). A benign or malignant brain and spinal cord tumor that arises from glial cells (astrocytes, oligodendrocytes, ependymal cells). "While TUBA1C and FBXO17 have been extensively studied in glioma and are known to promote tumor progression, TOM1L1's role in glioma remains underexplored, particularly in the context of PTM‐mediated mechanisms." (PMID 40090864, 2025). "The differential gene expression of FBXO17 has been found in numerous diseases, including breast cancer and gliomas." (PMID 35453806, 2022). "In general, it has been proved that FBXO17 is overexpressed in many kinds of tumors, like glioma, HCC, lung adenocarcinoma and esophageal squamous cell carcinoma." (PMID 33622332, 2021). "Patients with elevated FBXO17 have a worse prognosis in multiple cancers, such as high-grade glioma and hepatocellular carcinoma." (PMID 34531901, 2021). "After validation by RT-qPCR, IGF2BP3, NSUN7, EXO1, and FBXO17 had higher expression levels in glioma than controls." (PMID 33634155, 2021). "Furthermore, we also measured the protein levels of four selected RBPs (GNL1, SPATS2L, RDM1, and FBXO17) in three glioma cell lines, one astrocytoma cell line (SW1088) and two glioblastoma cell lines (U251 and LN229)." (PMID 33634092, 2020). "High FBXO17 expression could independently predict the clinical outcomes for high-grade glioma." (PMID 33634155, 2021). "Our data confirmed the up-regulation of ANG, EXO1, FBXO17, IGF2BP3, and NSUN7 in glioma than normal samples (all p < 0.0001)." (PMID 33634155, 2021). "The results showed that ANG, EXO1, FBXO17, IGF2BP3, and NSUN7 displayed distinctly higher expression levels in glioma compared to controls (p < 0.05)." (PMID 33634155, 2021). "Our data suggested that IGF2BP3, NSUN7, EXO1, and FBXO17 were highly expressed in AC-, MES-, NPC-, and OPC-like malignant cells, which could be related to poor prognosis for glioma patients." (PMID 33634155, 2021).
lung adenocarcinoma (4 papers, 2018 to 2022). A carcinoma that arises from the lung and is characterized by the presence of malignant glandular epithelial cells. "Tomeka et al27 recently evaluated FBXO17 expression in lung adenocarcinoma cells, where it was observed that it accelerated the progression of the tumor by regulating the PI3K-Akt-mTOR pathway." (PMID 36035375, 2022). "Recent studies have showed that overexpression of FBXO17 increases cell proliferation coupled with Akt activation in lung adenocarcinoma." (PMID 33622332, 2021). "Here, we identified that in several lung adenocarcinoma cell lines, FBXO17 cellular protein was detected at relatively high levels, as was expression in a subset of lung cancers." (PMID 30359271, 2018). "FBXO17 could promote liver cancer progression via the Wnt/β-catenin pathway and accelerate lung adenocarcinoma cell proliferation by activating the Akt pathway." (PMID 33634092, 2020).
hepatocellular carcinoma (3 papers, 2021 to 2024). A malignant tumor that arises from hepatocytes. "Studies have shown that the expression of FBXO17 is significantly elevated in the tumor tissues of hepatocellular carcinoma (HCC) patients compared to adjacent normal tissues." (PMID 39544935, 2024).
adenoid cystic carcinoma of the salivary gland (1 paper, 2018). "FBXO17, encoding F-box protein 1, is known to be involved in ubiquitination and glycoprotein catabolism and was reported to be hypomethylated in adenoid cystic carcinoma of the salivary gland." (PMID 30064493, 2018).
endometrial carcinoma (1 paper, 2022). A malignant tumor arising from the epithelium that lines the cavity of the uterine body. "The proportion of FBXO17-low expression in endometrial carcinoma samples was significantly higher compared with the paracancerous tissue (65.6% vs 35.6%)." (PMID 36035375, 2022). "Additionally, markedly low expression of FBXO17 was observed in endometrial carcinoma tissues (n=90) using IHC compared with the paracancerous tissues (n=90)." (PMID 36035375, 2022).
endometrial tumor (1 paper, 2022). "In conclusion, these findings indicate that FBXO17 is a novel inhibitor of endometrial tumor development and it likely exerts effects via regulation of the Wnt signaling pathway." (PMID 36035375, 2022).
lung carcinoma (1 paper, 2018). "An association was found between FBXO17 expression and lung cancer using the large Cancer Genome Atlas cohort." (PMID 30359271, 2018). "Multiple lung cancer cell lines were immunoblotted, and The Cancer Genome Atlas was analyzed to determine if FBXO17 expression was amplified in a subset of lung cancers." (PMID 30359271, 2018). "A subset of lung cancers highly express FBXO17 mRNA transcript and protein, and our data show that FBXO17 promotes robust cell proliferation and cell cycle progression that is potentially relevant in non-small cell lung cancer." (PMID 30359271, 2018). "We also interrogated the cBio Cancer Genomics Portal and found that FBXO17 expression was increased in 5% of all lung cancer samples in the database (n = 1144)." (PMID 30359271, 2018). "Indeed, FBXO17 was detected at high levels in many lung carcinoma cell lines and its transcript is highly expressed in squamous cell lung cancer." (PMID 30359271, 2018). "We first examined if FBXO17 was overexpressed or altered in lung cancer cell lines." (PMID 30359271, 2018). "High FBXO17 expression, however, drives cell proliferation and may be relevant in the context of lung cancer and aberrant cell proliferation." (PMID 30359271, 2018). "Because Akt phosphorylates and negatively regulates GSK3β, a potentially important association that might impact cell growth and survival, we tested the hypothesis that FBXO17, highly expressed in lung carcinoma, regulates cell proliferation through Akt activation." (PMID 30359271, 2018).
non-small cell lung carcinoma (1 paper, 2018). A group of at least three distinct histological types of lung cancer, including non-small cell squamous cell carcinoma, adenocarcinoma, and large cell carcinoma. "Single cell RNA sequencing analysis was performed on a resection of a non-small cell lung carcinoma tumor to examine FBXO17 expression." (PMID 30359271, 2018).
cancer (8 papers, 2018 to 2024). A tumor composed of atypical neoplastic, often pleomorphic cells that invade other tissues. "Overexpression of FBXO17 is significantly associated with poor prognosis of these cancer patients." (PMID 33622332, 2021). "In summary, several genes shown to be differentially expressed when FBXO17 is depleted are implicated in metabolic and cell proliferative functions that may provide further insight into the role of this poorly studied F-box protein in cancer biology." (PMID 30359271, 2018). "The FBXO17 overexpressing group had a relatively low cancer cell density as well as Ki67 expression compared with the negative control group." (PMID 36035375, 2022). "FBXO17 was found to be upregulated in tumor tissues and promote malignant progression of cancer through different mechanisms, such as activation of Akt, or wnt/β-catenin pathway." (PMID 34531901, 2021). "Meanwhile, the F-box protein (FBXO17) may inhibit the Wnt/β-catenin signaling pathway, thus influencing cancer progression." (PMID 37915947, 2023). "FBXO17 primarily plays an oncogenic role in various cancers." (PMID 34702278, 2021). "FBXO17 expression appears to be advantageous for tumor cell survival, and we propose that upregulation of Akt activation by this F-box protein is a potential mechanism for increased mTOR activation in cancer." (PMID 30359271, 2018).
tumor (5 papers, 2018 to 2025). "The results of the analysis showed that FBXO17 mRNA was significantly lower in UCEC samples compared with the non-tumor endometrial tissues (P<0.001)." (PMID 36035375, 2022). "Tumor weight at the end of the experiment (day 27) was consistently lower in the FBXO17 overexpression group (P<0.001)." (PMID 36035375, 2022). "Additionally, the mean density of Ki67 expression was negatively associated with that of FBXO17 expression, which indicated that increased FBXO17 expression was a negative factor for tumor proliferation." (PMID 36035375, 2022). "We have also tested the mRNA expression of apoptosis-relevant genes (BAX, BCL-2 and CASP3) in tumor tissues of our model mice, and a TUNEL assay in tissue slices, which revealed an elevated apoptosis tendency in FBXO17-overexpressed mice implanted tumor." (PMID 36035375, 2022). "Pathway analysis revealed decreased expression of nine genes involved in cell proliferation and metabolism of tumor cell lines, indicating a role for upstream inhibition of the transcriptional regulator ATF4 and upstream activation of let-7 in our model of FBXO17 knockdown." (PMID 30359271, 2018).
adenocarcinoma (1 paper, 2018). A common cancer characterized by the presence of malignant glandular cells. "he magnitude of some of the biological and biochemical processes observed here at times were modest, but can be partly explained by the observation that A549 cells that were used are derived from adenocarcinoma cells with high baseline FBXO17 protein." (PMID 30359271, 2018).
immune diseases (1 paper, 2022). "Various associations between expression changes in FBXO17 and immune diseases have been reported." (PMID 35453806, 2022).
FBXO17 also shares sentences with these, for which no sentence is quoted: esophageal squamous cell carcinoma (2 papers); astrocytoma (1); breast carcinoma (1); bronchogenic carcinoma (1); glioblastoma (1); liver cancer (1); squamous cell carcinoma (1); squamous cell lung carcinoma (1).